NEU1 (neuraminidase 1)
Diseases named in the same sentence as NEU1 in open-access papers (continued):
Sharing a sentence is not in itself a finding about the gene and the disease.
bladder cancer (5 papers, 2020 to 2024). "Taken together, these findings suggest that downregulated expression of NEU1 is responsible for the aberrant expression of sialic acids in bladder cancer, and is associated with bladder tumor progression." (PMID 32164705, 2020). "A recent study reported on Neu-1 suppressing bladder cancer progression by inhibiting the fibronectin-integrin α5β1 interaction and the Akt signaling pathway." (PMID 35326525, 2022). "Neu-1 overexpression was reported to decrease cell viability and increase apoptosis in bladder cancer cell lines." (PMID 35326525, 2022). "Expression of NEU1 in primary human bladder cancer tissue samples was estimated using bladder cancer tissue microarray." (PMID 32164705, 2020). "The down-regulation of NEU1 in bladder cancer cells was determined by high resolution liquid chromatography mass spectrometry (HR LC-MS)." (PMID 32164705, 2020). "To investigate the molecular function of NEU1 in bladder cancer, we cloned the NEU1 gene, transfected it into bladder cancer cell lines YTS-1 and T24, and thus generated transfectant cell lines YTS-1/NEU1 and T24/NEU1." (PMID 32164705, 2020). "In conclusion, our observations indicate that NEU1 is an important modulator of the malignant properties of bladder cancer cells; i.e., NEU1 inhibited cancer cell proliferation, induced apoptosis, and suppressed tumor formation both in vitro and in vivo." (PMID 32164705, 2020). "In the present study, downregulation of NEU1 was observed in bladder cancer cells and clinical samples, and NEU1 overexpression resulted in inhibition of proliferation, promotion of apoptosis, and inactivation of the Akt signaling pathway." (PMID 32164705, 2020). "Our observations indicate that NEU1 is an important modulator of the malignant properties of bladder cancer cells, and is a potential therapeutic target for prognosis and treatment of bladder cancer." (PMID 32164705, 2020). "The effects of sialidase NEU1 expression on proliferation and apoptosis of human bladder cancer cells were examined by western blot, RT-PCR, confocal imaging and flow cytometry." (PMID 32164705, 2020). "NEU1 is a potential therapeutic target for prognosis and treatment of bladder cancer." (PMID 32164705, 2020). "NEU1 expression was evaluated using TMAs, including a total of 44 pairs of primary human bladder cancer tissue samples with matched adjacent noncancerous tissues." (PMID 32164705, 2020). "NEU1 level was clearly higher in noncancerous bladder cells than in bladder cancer cells." (PMID 32164705, 2020).
cardiomyopathy (5 papers, 2021 to 2025). A disease of the heart muscle or myocardium proper. "This study sought to determine the role of neuraminidase 1 (NEU1) in DOX-induced cardiomyopathy and the potential cardio-protective effects of NEU1 inhibitor oseltamivir (OSE)." (PMID 34977042, 2021). "This work identified NEU1 as a crucial inducer of DOX-induced cardiomyopathy by promoting Drp1-dependent mitochondrial fission and mitophagy, and NEU1 inhibitor showed new indications of cardio-protection against DOX cardiotoxicity." (PMID 34977042, 2021). "In this study, we proposed the hypothesis that NEU1 was a mediator of DOX-induced cardiomyopathy and NEU1 inhibitor could improve DOX-induced cardiac dysfunction through modulating Drp1-dependent mitochondrial fission and mitophagy." (PMID 34977042, 2021). "Importantly, our analysis of public GEO databases—specifically GSE246548, GSE247345, GSE23598, GSE107113 and GSE157282—revealed a significant negative correlation between multiple glycolysis‐related genes and Neu1 in cases of chemotherapeutic‐induced cardiomyopathy." (PMID 40411250, 2025). "Similarly, NEU1 protein levels were increased in cardiomyocytes in the STZ mouse model of diabetic cardiomyopathy, and NEU1 silencing protected against STZ-induced cardiomyopathy and myocardial fibrosis, inflammation, and apoptosis through an AMPK-SIRT3 pathway." (PMID 35479093, 2022). "In DOX-induced cardiomyopathy in rat models, DRP1 expression was increased by the elevated NEU1, which subsequently boosted mitochondrial fission and PINK1/Parkin pathway-mediated mitophagy." (PMID 37602332, 2023). "In this study, we uncovered that NEU1 acted as a critical driver of DOX cardiotoxicity, and NEU1 inhibitor had potentials to effectively improve cardiac dysfunction in DOX-induced cardiomyopathy by suppressing Drp1-mediated mitochondrial fission and mitophagy." (PMID 34977042, 2021). "Third, although the cardio-protective effect of NEU1 inhibitor against DOX-induced cardiomyopathy was remarkable in animal models, a large number of clinical trials are needed to confirm the efficacy of existing anti-viral drugs like OSE in DOX-induced cardiomyopathy treatment." (PMID 34977042, 2021). "Therefore, we hold the belief that NEU1 inhibitor could suppress myocardial apoptosis through inhibiting Drp1-mediated excessive mitochondrial fission and mitophagy, subsequently delaying the development of DOX-induced cardiomyopathy." (PMID 34977042, 2021).
influenza (5 papers, 2019 to 2025). An acute viral infection of the respiratory tract, occurring in isolated cases, in epidemics, or in pandemics; it is caused by serologically different strains of viruses (influenzaviruses) designated A, B, and C, has a 3-day incubation period, and usually lasts for 3 to 10 days. "Oseltamivir phosphate (OP) is a drug used to treat and prevent influenza, which specifically inhibits NEU1." (PMID 40196362, 2025). "Another identified drug, oseltamivir-phosphate, traditionally used to treat influenza infections, was found to target the Neu1 gene, the mechanism of which in oral tumorigenesis remains unstudied." (PMID 39857718, 2025). "Different retrospective studies in conditions with accelerated platelet clearance, such as anti-GPIb antibody-mediated ITP or suspected influenza, and an open-label randomized trial in sepsis, have supported the notion that Neu-1 inhibition by oseltamivir increases platelet counts." (PMID 34995275, 2022).
renal fibrosis (5 papers, 2023 to 2025). A final common manifestation of a wide variety of chronic kidney diseases characterized by glomerulosclerosis and tubulointerstitial fibrosis. "PCR array, co-immunoprecipitation, and surface plasmon resonance (SPR) were employed to investigate the underlying mechanisms by which NEU1 promotes renal fibrosis." (PMID 36973294, 2023). "As evidenced by studies with clinical samples and animal and cellular models of renal fibrosis, NEU1 is significantly upregulated in renal fibrotic conditions." (PMID 39194692, 2024). "In drug screens, the plant-derived compound salvianolic acid B from Salvia miltiorrhiza binds strongly to NEU1, setting off signaling cascades that protect mice from renal fibrosis in a NEU1-dependent manner." (PMID 39194692, 2024). "In this work, we demonstrated that NEU1 was noticeably elevated in patients with renal fibrosis, in mice subjected to UUO or administered folic acid, and in TGFβ-stimulated human tubular epithelial HK-2 cells." (PMID 36973294, 2023). "Here, the authors show that neuraminidase 1 promotes renal fibrosis development by interacting with ALK5 to activate SMAD2/3." (PMID 36973294, 2023). "The correlation analysis identified top 20 enriched KEGG pathways that are potential to be involved in NEU1-mediated renal fibrosis." (PMID 36973294, 2023). "In conclusion, this study identifies a promotor role for NEU1 in renal fibrosis and suggests a potential therapeutic approach by targeting NEU1 to treat CKD." (PMID 36973294, 2023). "TEC-specific NEU1 knockout and overexpression mice were generated to characterize the role of NEU1 in renal fibrosis progression." (PMID 36973294, 2023). "When ALK5 was knocked down, NEU1 overexpression-induced KIM1 and ALK5-SMAD2/3 signaling pathway activation were abolished in HK-2 cells, indicating that NEU1 promoted renal fibrosis in an ALK5-dependent manner." (PMID 36973294, 2023). "Collectively, this study characterizes a promotor role for NEU1 in renal fibrosis and suggests a potential avenue of targeting NEU1 to treat kidney diseases." (PMID 36973294, 2023). "We detected the neuraminidase 1 (NEU1) expression in patients with renal fibrosis, and in mice subjected to unilateral ureteral obstruction (UUO) or administered folic acid." (PMID 36973294, 2023). "Salvianolic acid B, a component of Salvia miltiorrhiza, is found to strongly bind to NEU1 and effectively protect mice from renal fibrosis in a NEU1-dependent manner." (PMID 36973294, 2023). "This study identified a key role for TEC-located NEU1 in renal injury and renal fibrosis based on the results of genetic, in vivo, in vitro, and pharmacological experiments." (PMID 36973294, 2023). "Although the influence of neuraminidases in other renal cell types such as myofibroblasts cannot be totally excluded in renal fibrosis, this work sheds light on a clear promotor role for tubular NEU1 in renal injury." (PMID 36973294, 2023). "This regulatory mechanism may parallel findings in the renal fibrosis model, where NEU1 has been observed to affect the ALK5 phosphorylation." (PMID 40411250, 2025). "On the other hand, the overexpression of the NEU1 gene exacerbated progressive renal fibrosis." (PMID 39194692, 2024). "Conversely, NEU1 overexpression exacerbates progressive renal fibrosis." (PMID 36973294, 2023). "NEU1 expression was also increased in the kidneys of folic acid-induced renal fibrosis." (PMID 36973294, 2023). "Within models of unilateral ureteral ligation (UUO) and folic acid (FA) stimulation, NEU1 knockout was effective in inhibiting epithelial/mesenchymal transition, inflammatory cytokine production, and collagen deposition, thus alleviating renal fibrosis and renal injury." (PMID 39194692, 2024). "Here, we characterize the role of neuraminidase 1 (NEU1) in unilateral ureteral obstruction (UUO) and folic acid (FA)-induced renal fibrosis mouse models." (PMID 36973294, 2023).
renal fibrosis (continued). "In this work, we have demonstrated that NEU1 was activated in the cytoplasm to bind to ALK5, promoting renal fibrosis." (PMID 36973294, 2023). "Collectively, these results suggested that NEU1 interacted with the GS domain (amino acids 160–200) of ALK5 in cytoplasm, and then enhanced the ALK5-SMAD2/3 signaling pathway, contributing to renal fibrosis." (PMID 36973294, 2023). "Immunohistochemistry and immunofluorescence revealed that NEU1 protein levels were significantly higher in patients with renal fibrosis than without renal fibrosis." (PMID 36973294, 2023). "In Neu1 CKO mice, treatment of salvianolic acid B (40 mg/kg) failed to further reduce renal injury and renal fibrosis in response to UUO stimulation, as evidenced by HE and Masson staining." (PMID 36973294, 2023).
breast carcinoma (4 papers, 2020 to 2022). "Consequently, NEU-1 could represent a common target that could be used to treat putative MS-associated cancers like colorectal, hepatocellular and postmenopausal breast cancer." (PMID 36230790, 2022). "As the biological effects of EDPs are linked to the NEU-1 activity, several studies have evaluated the role of NEU-1 in breast carcinoma cells." (PMID 36230790, 2022). "The NEU-1 inhibition by oseltamivir phosphate or its downregulation can impair the proliferation, apoptosis and epithelial-mesenchymal transition of breast cancer cells, and then, it can change the sialic acid level." (PMID 36230790, 2022). "Taken together, this literature suggests that NEU-1 plays an important role in breast cancer progression." (PMID 36230790, 2022). "Blocking Neu-1 with oseltamivir phosphate (Tamiflu®) or a Neu-1 siRNA in mammary carcinoma cells, MCF-7, and MDA-MB-231 cell lines, inhibits cell growth." (PMID 32351895, 2020). "Neu-1 regulates breast cancer cell proliferation and invasion." (PMID 32351895, 2020).
diabetic cardiomyopathy (4 papers, 2022 to 2025). Diabetic cardiomyopathy is a disorder of the heart muscle in people with diabetes. "In summary, the present study identified NEU1 deficiency attenuated STZ-induced diabetic cardiomyopathy." (PMID 35002528, 2022). "Despite their shared the cardioprotective effects of NEU1 deficiency in different cardiovascular diseases, our study contributes to supplement of the specific mechanism of NEU1 in the pathogenesis of diabetic cardiomyopathy." (PMID 35002528, 2022). "NEU1 deficiency attenuates cardiac dysfunction, oxidative stress, fibrosis, and inflammation through the AMPK-SIRT3 signaling pathway in diabetic cardiomyopathy mice." (PMID 40221400, 2025). "Our data suggested that NEU1 inhibition exert its protective effect against diabetic cardiomyopathy via LKB1-AMPKα-SIRT3 pathway." (PMID 35002528, 2022). "To investigate whether NEU1 is involved in the pathogenesis of diabetic cardiomyopathy, we first detected NEU1 expression levels by Western blot." (PMID 35002528, 2022). "Here, the aims of the present study were 1) to determine whether NEU1 is involved in the pathological process of diabetic cardiomyopathy, 2) to identify how does NEU1 affect the development of DCM, and 3) the specific molecular mechanism of NEU1 affecting DCM." (PMID 35002528, 2022).
Hyperglycemia (4 papers, 2022 to 2025). An increased concentration of glucose in the blood. "Clinically, observational studies associate oseltamivir with hyperglycemia, worsening glycemic control, and delayed-onset adverse events, including neuropsychiatric symptoms and metabolic disturbances, suggesting that its inhibition of Neu-1 disrupts metabolic homeostasis." (PMID 39861189, 2025). "Studies using sialidase inhibitors like 2-deoxy-2,3-dehydro-N-acetylneuraminic acid (DANA) and animal models with Neu-1 knockout or overexpression show that inhibiting Neu-1 leads to hyperglycemia and impaired glucose tolerance." (PMID 39861189, 2025). "Therefore, cardiac specific silencing NEU1 does not affect insulin sensitivity or hyperglycemia." (PMID 35002528, 2022).
lupus nephritis (4 papers, 2020 to 2024). Glomerulonephritis in the context of systemic lupus erythematosus. "NEU1 is also responsible for coordinating inflammatory responses in lupus glomerulonephritis, such as the release of tumor necrosis factor-α (TNF-α) and interleukin-6 (IL-6)." (PMID 39194692, 2024). "Further scrutiny is warranted to clarify the roles and mechanisms of GSL metabolism, sialylated glycans, and NEU1 activity in lupus glomerulonephritis." (PMID 39194692, 2024). "For instance, NEU1 regulates the formation and deposition of immune complexes in cellular events, leading to lupus glomerulonephritis." (PMID 39194692, 2024). "As a regulator of cytokine release in autoimmunity, NEU1 is etiologically significant to the pathogenesis of lupus glomerulonephritis." (PMID 39194692, 2024). "NEU1 immunohistochemical staining and urinary excretion were significantly elevated in lupus nephritis patients compared with controls." (PMID 35479093, 2022). "In human studies, proteomic analysis of renal tissues comparing patients with proliferative lupus nephritis vs. healthy controls revealed NEU1 as the greatest up-regulated protein of 48 identified proteins." (PMID 35479093, 2022). "A growing body of evidence suggests a role for NEU1 in the pathogenesis of lupus nephritis." (PMID 35479093, 2022). "Specifically, NEU1 was elevated in most types of CKD including IgA (n = 25), diabetic kidney disease (n = 17), lupus nephritis (n = 32), focal segmental glomerulosclerosis (n = 17), and membranous glomerulonephritis (n = 18), but not in minimal change disease (n = 14)." (PMID 36973294, 2023).
Lysosomal disease (4 papers, 2016 to 2024). "The involvement of NEU1 in lysosomal diseases clearly demonstrates that NEU1 functions as a lysosomal enzyme and is supported by its optimal acidic pH for catalysis." (PMID 27917893, 2016). "While the mechanism of the dysfunction of the NEU1 deficiency-induced bone and muscle formation has been sufficiently studied, little is known about the involvement of NEU1 in emotional regulation, unlike other lysosomal diseases." (PMID 34188220, 2021).
parasite infection (4 papers, 2019 to 2025). "Meanwhile, genes related to cancer metastasis, such as Tns4, Neu1, Serpina10, and Trib3 (54, –, 57), as well as Mcpt1 and Mcpt2, which are associated with parasitic infections, were significantly upregulated after infection." (PMID 39727670, 2025). "To specifically pinpoint the effect of Neu1 on TLR4 during parasite infection, we overexpressed Neu1 in macrophage by transfecting a plasmid encoding the Neu1 gene followed by infection with parasite." (PMID 31649671, 2019). "The current study thus demonstrated that differential activation of TLR4-pathways during this parasite infection is under the dual regulation of Neu1 and siglec-E through their action on a common sugar namely sialic acids." (PMID 33763070, 2021). "Parasite infection of Neu1-transfected macrophages increased the expression of IKKα and IKKβ in the cytosolic fraction." (PMID 31649671, 2019). "Accordingly, here we addressed the role of Neu1 in immune modulation during this parasite infection." (PMID 31649671, 2019). "We observed a significantly (p ≤ 0.05) enhanced iNOS expression of 2.3-fold in Neu1-transfected cells after parasite infection." (PMID 31649671, 2019). "This establishes a probable correlation between the ability of Neu1 translocation on the cell surface with successful parasite infection." (PMID 31649671, 2019). "Therefore, decreased Neu1 and increased α2,3-linked sialic acids on TLR4 plays an important role to ascertain successful parasite infection in the host cells." (PMID 31649671, 2019). "Thus, we have established a possible link between the enhanced TLR4 sialylation mediated by reduced membrane-bound Neu1 during this parasite infection." (PMID 31649671, 2019). "Thus, we observed a good correlation between Neu1-mediated desialylation of TLR4 and activation of the MAPK pathway in addition to NF-κB nuclear translocation indicating higher cellular activation thereby possible inhibition of parasite infection in presence of enhanced Neu1." (PMID 31649671, 2019). "We, therefore, checked the relevance of Neu1 and siglec-E on TLR4 activation during parasite infection." (PMID 33763070, 2021).